DBNL (drebrin like)
Description:
Adapter protein that binds F-actin and DNM1, and thereby plays a role in receptor-mediated endocytosis. Plays a role in the reorganization of the actin cytoskeleton, formation of cell projections, such as neurites, in neuron morphogenesis and synapse formation via its interaction with WASL and COBL. Does not bind G-actin and promote actin polymerization by itself. Required for the formation of organized podosome rosettes (By similarity). May act as a common effector of antigen receptor-signaling pathways in leukocytes. Acts as a key component of the immunological synapse that regulates T-cell activation by bridging TCRs and the actin cytoskeleton to gene activation and endocytic processes.
Synonyms: HIP-55; SH3P7; ABP1; HIP55
Tractability: Antibody: UniProt places it where antibodies can reach, with high confidence; its Gene Ontology location is reachable by antibodies, with high confidence; the Human Protein Atlas places it where antibodies can reach. PROTAC: ubiquitination databases record sites on it; its protein half-life has been measured.
Gene: Protein-coding gene on chromosome 7 (44,044,628 to 44,069,456, forward strand). Ensembl gene ENSG00000136279.
Subcellular location: Cytoplasm, cytoskeleton; Cell projection, lamellipodium; Cell projection, ruffle; Cytoplasm, cell cortex; Cytoplasm, cytosol; Synapse; Perikaryon; Cell projection, neuron projection; Cell membrane; Cytoplasmic vesicle, clathrin-coated vesicle membrane; Golgi apparatus membrane; Cell projection, podosome; Early endosome; Cell projection, dendrite; Postsynaptic density
Subcellular location (Human Protein Atlas): Plasma membrane; Vesicles
Pathways (Reactome):
Immune System: Neutrophil degranulation
Neuronal System: Neurexins and neuroligins
Programmed Cell Death: Caspase-mediated cleavage of cytoskeletal proteins
Gene Ontology:
Molecular function: cadherin binding; protein binding; actin binding; actin filament binding; enzyme activator activity; protein-macromolecule adaptor activity; protein domain specific binding; structural constituent of postsynaptic actin cytoskeleton
Biological process: endocytosis; membrane organization; neuron projection morphogenesis; podosome assembly; Rac protein signal transduction; synapse assembly; postsynaptic actin cytoskeleton organization
Cellular component: cytoplasm; early endosome; extracellular exosome; plasma membrane; cell cortex; cytosol; extracellular region; ficolin-1-rich granule lumen; Golgi membrane; lamellipodium; membrane; perikaryon; podosome; postsynaptic density; ruffle; secretory granule lumen; synapse; tertiary granule lumen; clathrin-coated vesicle membrane; cytoskeleton; dendrite; glutamatergic synapse; neuron projection; postsynapse; presynapse
Genetic constraint (gnomAD): Loss-of-function variants: 35 observed, 59.35 expected, observed/expected ratio (o/e) 0.59, 90% interval 0.45 to 0.78. The upper end of that interval is the gene's LOEUF score, 0.78, which puts it in group 3 of 6, group 1 being the genes least tolerant of losing a copy. Missense variants: 495 observed, 577.31 expected, observed/expected ratio (o/e) 0.86, 90% interval 0.8 to 0.92. Synonymous variants: 197 observed, 213.54 expected, observed/expected ratio (o/e) 0.92, 90% interval 0.82 to 1.04.
Homologues: Orthologues: chimpanzee DBNL (99% identical), macaque DBNL (93% identical), guinea pig DBNL (88% identical), mouse Dbnl (86% identical), pig DBNL (86% identical), rat Dbnl (85% identical), dog DBNL (82% identical), tropical clawed frog dbnl (62% identical), zebrafish dbnlb (60% identical), zebrafish dbnla (52% identical). Paralogues in human: DBN1 (31% identical), CTTN (23% identical), HCLS1 (20% identical), COTL1 (9% identical).
Diseases named in the same sentence as DBNL in open-access papers:
DBNL is named in the same sentence as 22 diseases in open-access papers, as found by Europe PMC text mining. Sharing a sentence is not in itself a finding about the gene and the disease. The quoted sentences say what the papers report.
breast carcinoma (3 papers, 2018 to 2020). "DBNL is a cytosolic adaptor protein and putative suppressor of breast cancer metastasis." (PMID 30022044, 2018).
lung adenocarcinoma (2 papers, 2014 to 2020). A carcinoma that arises from the lung and is characterized by the presence of malignant glandular epithelial cells. "Here, we report the functional characterization of hematopoietic progenitor kinase 1 (HPK1)-interacting protein of 55 kDa (HIP-55)/Drebrin-like (DBNL), which was identified in a 14-3-3γ affinity resin-based proteomic approach using lung adenocarcinoma A549 cells." (PMID 24912570, 2014).
Cerebral ischemia (1 paper, 2021). Restriction of arterial blood supply to the brain associated with insufficient oxygenation to support the metabolic requirements of the tissue. "In this study, we aimed to identify the regulatory factors (cofilin-1, Arp2/3, and drebrin-like) of actin cycling/turnover related to cerebral ischemia-reperfusion." (PMID 33777942, 2021). "Although previous studies found that ARP2/3 and DBNL exhibit significant changes after cerebral ischemia, we determined that the mRNA and protein levels of ARP2/3 and DBNL exhibit changes, but they are not significant." (PMID 33777942, 2021).
colorectal cancer (1 paper, 2023). A primary or metastatic malignant neoplasm that affects the colon or rectum. "Synaptopodin-2 and the Isoform 2 of Drebrin-like protein are actin-binding proteins known to be respectively invasive cancer biomarkers and potential markers for breast, lung, and colorectal cancers." (PMID 37775701, 2023).
dilated cardiomyopathy (1 paper, 2021). Cardiomyopathy which is characterized by dilation and contractile dysfunction of the left and right ventricles. "The hsa-mir-1254 and its target gene DBNL regulate cell proliferation and immune responses, and increased expression of DBNL has been reported in experimental dilated cardiomyopathy." (PMID 34926599, 2021).
encephalitis (1 paper, 2023). An acute inflammatory process affecting the brain parenchyma. "DBNL and RIN3 have been shown to be autoantigenic in neurologic diseases like encephalitis and schizophrenia respectively." (PMID 37244972, 2023).
cancer (5 papers, 2012 to 2021). A tumor composed of atypical neoplastic, often pleomorphic cells that invade other tissues. "To characterize the biological function of DBNL in human cancer, we first examined in vivo phosphorylation status of DBNL by western blot analysis using BT549 cells treated with Okadaic acid that can inhibit the phosphatase activity." (PMID 23283305, 2012). "In detail, MBNL1 could suppress cancer metastasis via binding to the 3′ untranslated regions (UTRs) of DBNL in breast and contribute to the carcinogenesis in the form of miRNA-MBNL1 in colorectum." (PMID 29383134, 2017). "Since membrane ruffling is related to tumor cell mobility and cancer metastasis, we performed Matrigel invasion assay and observed significantly higher invasiveness of the cells overexpressing both DBNL and MELK than the control cells or those overexpressing either of the two genes." (PMID 23283305, 2012).
DBNL also shares sentences with these, for which no sentence is quoted: tumor (4 papers); heart failure (3); lung carcinoma (2); adenocarcinoma (1); cardiac hypertrophy (1); large cell carcinoma (1); lymph node metastasis (1); myocardial infarction (1); neurologic diseases (1); pancreatic cancer (1); schizophrenia (1); Splenomegaly (1); squamous cell carcinoma (1); squamous cervical cancer (1); Stroke (1).